SKP2 (S-phase kinase associated protein 2)
Diseases named in the same sentence as SKP2 in open-access papers (continued):
Sharing a sentence is not in itself a finding about the gene and the disease.
breast carcinoma (continued). "A recent study showed that the S-phase kinase-associated protein 2 (SKP2) promotes PDCD4 phosphorylation at Ser67 and subsequently its proteasomal degradation, resulting in the promotion of breast cancer cell proliferation." (PMID 35795053, 2022). "SKP2 has been proved to be an oncogene, which is overexpressed in prostate cancer, melanoma, nasopharyngeal carcinoma, and breast cancer." (PMID 35831273, 2022). "Breast cancer: curcumin reduced expression of Skp2, Her2, cyclin E, and CDK kinases in MDA-MB-231/Her2 cells." (PMID 36712505, 2022). "Since the oncogenic role of SKP2 in breast cancer (BC) in particular is well established, here we focus our study on this disease." (PMID 35169199, 2022). "It is also reported that SKP2 has an anti-tumor effect on various types of cancers, such as breast cancer, lung cancer, osteosarcoma, and so on." (PMID 35865382, 2022). "On the one hand, knockout of SKP2 significantly increased the sensitivity of Her2 positive breast cancer cells to Herceptin, on the other hand, SKP2 silencing or inactivation can restore non-small cell lung cancer sensitivity to gefitinib treatment." (PMID 35831273, 2022). "In human breast cancer tissues, we also found a positive correlation between the levels of SKP2 and p97." (PMID 33731668, 2021). "For instance, YAP-driven proliferation in breast cancer cells depends on SKP2 expression: upon YAP inactivation, the downregulation of Skp2 and the consequential accumulation of p21 and p27 (which are degraded in a Skp2-dependent way) induce a cell cycle exit." (PMID 34439395, 2021). "The Skp2-SCF E3 ligase was identified to be engaged in EGF-stimulated Akt ubiquitination in breast cancer cells." (PMID 34409101, 2021). "Acquisition of EMT is associated with Skp2 expression in paclitaxel-resistant (PR) breast cancer cells, and Skp2 modulates molecular markers of EMT, including E-cadherin, Vimentin, Snail, and Slug, to enhance tumor metastasis." (PMID 34068643, 2021). "Vorinostat enhances the protein stability of p27 and p21 by negative regulation of Skp2 and Cks1 in human breast cancer cells." (PMID 34068643, 2021). "SMIP004 can even decrease the protein stability of PCAN, which is the target of Skp2, and inhibit breast cancer cell proliferation." (PMID 35006464, 2021). "Silence of Skp2 or inhibition Skp2 by pharmaceutic inhibitors significantly improves breast cancer cell sensitivity to the anti-breast cancer drug, Gefitinib." (PMID 33661942, 2021). "In breast cancer, CAF-secreted kynurenine, a tryptophan metabolite, was found to promote E-cadherin/Aryl hydrocarbon receptor (AhR)/S-phase kinase-associated protein 2 (Skp2) complex, leading to E-cadherin degradation, which supported cancer cell invasion." (PMID 33540679, 2021). "Over-expression of Skp2 is related to resistance to preoperative DOX-based chemotherapy in primary breast cancer." (PMID 34068643, 2021). "Correspondingly, SKP2 up-regulation has been observed in many cancers like malignant oral cancer 37, colorectal cancer 38, hepatocellular carcinoma 18, and breast cancer." (PMID 32226545, 2020). "In the current study, our data suggest that diosgenin is a potential inhibitor of Skp2 in breast cancer." (PMID 32626765, 2020). "A recent study reported that NONO in breast cancer regulates the expression of S-phase-associated kinase 2 (SKP2) and E2F transcription factor 8 (E2F8) at the post-transcriptional level, promoting breast cancer proliferation." (PMID 32106418, 2020). "The upregulation of p57 and FOXO1 by diosgenin was further increased by Skp2 siRNA transfection in breast cancer cells." (PMID 32626765, 2020). "In the context of breast cancer, CDK8 along with S-phase kinase-associated protein 2 (Skp2) has been shown in tissue samples to positively correlate with stage of breast cancer." (PMID 33291686, 2020). "APC/C, Cdc20, Cdh1, βTrCP, and Skp2 are several E3 ligases that have been suggested to be potential therapeutic molecules in breast cancer." (PMID 32882786, 2020).
breast carcinoma (continued). "In our study, we found that diosgenin decreased the expression of Skp2 in breast cancer cells, resulting in attenuation of breast cancer cell proliferation and motility." (PMID 32626765, 2020). "In summary, diosgenin inhibited cell viability and motility via suppression of Skp2 in breast cancer cells." (PMID 32626765, 2020). "Mechanistically, we found that diosgenin decreased the expression of Skp2 at mRNA and protein levels in breast cancer cells." (PMID 32626765, 2020). "The enhanced expression of Skp2 was observed in breast and prostate cancer, thereby, therapeutic approaches combining radiotherapy and Skp2 targeting were suggested for breast cancer patients." (PMID 32882786, 2020). "Altogether, diosgenin mediated anticancer activity in part via suppression of Skp2 expression in breast cancer cells." (PMID 32626765, 2020). "In conclusion, SKP2 inhibitor can be used as a novel radiosensitizer in breast cancer clinical trials." (PMID 30760284, 2019). "SKP2 mRNA high expression was found to be correlated to significantly poor prognosis for breast cancer patients (Affymetrix ID: 203625_x_at, HR = 1.75 (1.57–1.96), p < 1e-16; Affymetrix ID: 203567_x_at, HR = 1.33 (1.19–1.49), p = 2.2e - 07)." (PMID 30760284, 2019). "Altogether, these results suggest that SKP2 regulates breast cancer cells proliferation and breast cancer development via inhibiting PDCD4 expression." (PMID 30760284, 2019). "SKP2 overexpression has been seen in multiple human cancers such as prostate cancer, pancreatic cancer, breast cancer, and melanoma." (PMID 31886205, 2019). "In summary, SKP2 enhances EMT in breast cancer and melanoma, whereas FBXL5 suppresses EMT in human gastric and cervical cancer cells, and FBXL14 is an EMT inhibitor in head and neck cancer cells." (PMID 30999935, 2019). "SKP2 stably overexpressed or knockdown breast cancer cell lines were established and western blot was used to detect proteins changes before and after radiation." (PMID 30760284, 2019). "SKP2 inhibitor SMIP004 combine with radiation treatment showed remarkable inhibitory effects on breast cancer cells." (PMID 30760284, 2019). "SMIP004, a SKP2 inhibitor, showed remarkable inhibitory effects after radiation in breast cancer by inducing cell apoptosis and inhibiting DNA-damage response." (PMID 30760284, 2019). "Radiotherapy combine with SKP2 inhibitor SMIP004 showed significant inhibitory effects on breast cancer cells in vitro and in vivo." (PMID 30760284, 2019). "SKP2 has been proved as an oncogene, which is overexpressed in lymphoma, prostate cancer, melanoma, nasopharyngeal carcinoma, breast cancer and so on." (PMID 30760284, 2019). "To determine the mechanism by which AC regulates the proliferation of breast cancer cells, we also determined the mRNA and protein expression of skp2 in the 2 breast cancer cells treated with AC." (PMID 29743060, 2018). "Activation of AMPK/Skp2 S256 phosphorylation/Akt axis in cancer drives cancer progression and drug resistance, leading to poor survival outcome of breast cancer patients." (PMID 30413706, 2018). "Our data suggested that AC inhibits growth in both ER-positive and tamoxifen-resistant breast cancer cells by modulating apoptosis and the protein and mRNA expressions of skp2." (PMID 29743060, 2018). "Previously, we identified that macroh2A is a new Skp2 SCF substrate, whose ubiquitination by Skp2 inhibits the proliferation, colony formation and migration in breast cancer cells." (PMID 28446188, 2017). "Herceptin plus FKA treatment leads to an enhanced growth inhibitory effect on HER-2 overexpressing breast cancer cell lines through downregulation of Myt1, Wee1, Skp2, survivin, and XIAP." (PMID 28335434, 2017). "Strikingly, we identified that rottlerin exhibited its anti-tumor potential partly through inactivation of Skp2 in breast cancer." (PMID 27582552, 2016).
breast carcinoma (continued). "More importantly, we identified that rottlerin-induced anti-cancer activity is partly through down-regulation of Skp2 pathway in breast cancer." (PMID 27582552, 2016). "The overexpression of SCF subunit Skp2 has been shown to contribute to tumorigenesis in prostate cancer, breast cancer and lymphoma." (PMID 27374082, 2016). "Consistently, overexpression of Skp2 by its cDNA transfection inhibited cell apoptosis in breast cancer cells." (PMID 27582552, 2016). "Altogether, rottlerin exerts its tumor suppressive function partly through down-regulation of Skp2 in breast cancer cells." (PMID 27582552, 2016). "In line with this, we observed the similar results, suggesting that Skp2 contributes to breast cancer cell growth." (PMID 27582552, 2016). "Uehara and colleagues demonstrated that the HDACi vorinostat enhanced protein stability of p27KIP1 and p21WAF1/KIP1, without concomitant induction of p27KIP1 mRNA, through negative regulation of Skp2 and Cks1 in human breast cancer cells." (PMID 27716272, 2016). "Mechanically, we observed that rottlerin significantly down-regulated the expression of Skp2 in breast cancer cells." (PMID 27582552, 2016). "In the current study, we observed that up-regulation of Skp2 promoted cell migration and invasion, while down-regulation of Skp2 retarded cell migratory activity in breast cancer cells." (PMID 27582552, 2016). "Real-time PCR and Western blotting were used to detect the expression of Skp2 at mRNA and protein levels, respectively, in breast cancer cells treated with rottlerin." (PMID 27582552, 2016). "SKP2 is considered to have strong independent prognostic potential and be a useful target for the treatment of breast cancer." (PMID 25530715, 2014). "Skp2 is overexpressed and associated with poor prognosis in variety of human cancers, including prostate cancer, gastric cancer, breast cancer, and liver cancer, suggesting the oncogenic role of Skp2 in tumorigenesis." (PMID 25015320, 2014). "Here we show that Skp2, an oncogene previously shown to be down-regulated in ligand treated breast cancer cells, is down-regulated in two sensitive PDAC cell lines as a consequence of GW3965 treatment." (PMID 25184494, 2014). "In this study, we aim to study the relationship between expression of cytoplasmic PPARγ and Skp2 expression in breast cancer, and investigate the mechanisms by which Skp2 regulates cytoplasmic localization of PPARγ." (PMID 23939428, 2013). "In this study, the role of cytoplasmic PPARγ and Skp2 expression was investigated in human breast cancer progression." (PMID 23939428, 2013). "The expression of cytoplasmic PPARγ was reduced in estrogen receptor positive (ER-positive) human breast cancer (well differentiated) correlating with weak Skp2 abundance." (PMID 23939428, 2013). "Using immunohistochemistry, we examined the clinical significance of cytoplasmic PPARγ and Skp2 in paraffin-embedded mammary tissue sections screened from twenty benign breast diseases and fifty breast cancer patients." (PMID 23939428, 2013). "Our data revealed that expression of cytoplasmic PPARγ was positively related with Skp2 expression, which is critical to the development and progression of breast cancer." (PMID 23939428, 2013). "A relationship between Skp2 expression level and a poor prognosis was also observed, for example, in B-cell lymphoma, and breast cancer." (PMID 23939428, 2013). "The typical case showed that the high expression of cytoplasmic PPARγ was correlated with high Skp2 expression in the same breast cancer specimen (ER-negative, PR-negative, stage III)." (PMID 23939428, 2013). "Skp2 plays an important role in breast cancer, and is also considered to have strong independent prognostic potential." (PMID 23939428, 2013). "We demonstrated for the first time that Skp2 overexpression provokes cytoplasmic localization of PPARγ upon MEK1-dependent mechanisms in human breast cancer cells." (PMID 23939428, 2013).
breast carcinoma (continued). "In this report, we studied the clinical significance and relationship between cytoplasmic localization of PPARγ and Skp2 expression in human breast cancer." (PMID 23939428, 2013). "Expression of the interacting genes in the PLK1-MCM complex-SKP2 subnet of breast cancer patient datasets is positively correlated in ER positive samples and ER negative samples." (PMID 22838965, 2012). "Thirty one genes are overlapped in the PLK1-MCM complex-SKP2 subnets of breast cancer patient datasets (37 genes in total) and the one of NSCLC patient datasets (42 genes in total)." (PMID 22838965, 2012). "On the other hand, Skp2 is found to be frequently overexpressed in various types of cancers including breast cancer." (PMID 23230084, 2012). "Increased cytoplasmic Skp2 expression correlated with p-Akt1 expression, with 54.2% (51/94) of low p-Akt1-expressing breast carcinomas, but 72.6% (114/157) of high p-Akt1-expressing breast carcinomas exhibiting cytoplasmic Skp2 expression." (PMID 23300741, 2012). "The pattern of Skp2 expression in breast cancers, as evidenced by immunohistochemistry, is highly heterogeneous." (PMID 23300741, 2012). "To investigate the role of cytoplasmic Skp2 expression in human breast carcinomas, we immnohistochemically assessed cytoplasmic Skp2, p-Akt1, and p27 expression in 251 patients with invasive ductal carcinomas of the breast." (PMID 23300741, 2012). "Analysis of the expression levels of Skp2 and β-TrCP in different prostate and breast cancer cell lines, including LNCaP, PC-3, DU-145, MCF-7, MDA-MB-231, and MDA-MB-468, revealed that these F-box proteins are differentially expressed among these cells." (PMID 23071779, 2012). "It has already been shown that Skp2 deficiency can enhance sensitivity of leukemia cells to chemotherapy and Skp2 is itself being increasingly considered a possible target for breast cancer and prostate cancer therapy." (PMID 23071715, 2012). "Among the SCF-type of E3 ubiquitin ligases, SCFSkp2 is one of the most well-studied E3 ligases and Skp2 overexpression is frequently observed in various types of human cancers including breast cancer." (PMID 23227454, 2012). "Being key players involved in regulation of the cell cycle, biologically plausible reports of p16, Skp2 and cyclin E overexpression in basal-like breast cancer have been made." (PMID 24281106, 2010). "Skp2 was found to be an oncogene and an independent prognostic marker for disease-free and overall survival in breast cancer." (PMID 18644126, 2008). "The expression levels of Skp2 and p27Kip1 were determined by immunohistochemistry both before and after preoperative chemotherapy in 40 patients with locally advanced breast cancer." (PMID 18644126, 2008). "The role of Skp2 as an oncogene responsible for downregulation of p27Kip protein levels is well established in a wide variety of cancers, including early breast cancer." (PMID 18644126, 2008). "Initially, we examined the expression of Skp2 and p27Kip1 in 40 tumor samples obtained from patients with locally advanced breast cancer before the initiation of preoperative chemotherapy." (PMID 18644126, 2008). "The expression of Skp2 mRNA and protein levels were examined in rapamycin-treated breast cancer cell lines." (PMID 16859513, 2006). "In the present study, we examined the effects of rapamycin on Skp2 expression in breast cancer lines and the regulatory mechanisms that determine its cellular abundance." (PMID 16859513, 2006). "Our results suggest that rapamycin down-regulates Skp2 expression in cultured breast cancer cell lines by interfering with gene transcription as well as by increasing its rate of protein degradation." (PMID 16859513, 2006). "Among these cell cycle regulatory proteins, the oncogenic role of Skp2 in breast cancer has been clearly demonstrated." (PMID 16859513, 2006).
breast carcinoma (continued). "The results of the present study provide additional insights into the mechanisms of action of rapamycin on cell cycle arrest in breast cancer cells through direct down-regulation of Skp2 expression." (PMID 16859513, 2006). "To examine the effect of rapamycin on the expression of Skp2, we initially tested this effect in T47D, a breast cancer cell line that showed high sensitivity to rapamycin in our initial experiments." (PMID 16859513, 2006). "It was suggested that Skp2 acts as an oncogene in breast cancer and thus is overexpressed by increased transcriptional activity." (PMID 16859513, 2006). "The role of Skp2 as the main rate limiting regulator for the degradation of p27 has been clearly shown in several human cancers, including breast cancer." (PMID 16859513, 2006). "We studied the expression of Cks1, Skp2, and p27Kip1 by immunohistochemistry in 50 tumor samples obtained from patients with breast cancer." (PMID 16168119, 2005). "The present study was undertaken to examine the role of Cks1 expression in breast cancer and its relation to p27Kip1 and Skp2 expression and to tumor aggressiveness." (PMID 16168119, 2005). "The expressions of Cks1, Skp2, and p27Kip1 were examined immunohistochemically on formalin-fixed, paraffin-wax-embedded tissue sections from 50 patients with breast cancer and by immunoblot analysis on breast cancer cell lines." (PMID 16168119, 2005). "In the present study, we investigated the expression of Cks1 in relation to Skp2 and p27Kip1 and prognosis in breast cancer." (PMID 16168119, 2005). "Moreover, Western blotting and quantitative immunofluorescence in three breast cancer cell lines confirmed that PD-L1 is an upstream regulator of Livin, Galectin-1, and SKP2 protein expression." (PMID 41898602, 2026). "Our results also demonstrate that DCAF13 and SKP2 play essential roles in breast cancer prognosis." (PMID 39781342, 2025). "Phosphorylation of Ser72 by Akt and acetylation of K68 and K71 mediated by p300 contribute to the cytoplasmic localization and stability of Skp2, subsequently leading to the degradation of p27Kip1 and E-cadherin in breast cancer, prostate cancer, and liver cancer." (PMID 38561375, 2024). "Interestingly, we found that in human breast cancer samples, Runx2 and Skp2 are significantly increased and miR-137 and miR-340 are decreased, which is in line with the findings from the FS to BD diet comparison." (PMID 38059614, 2024). "The overexpression of Skp2 is associated with AKT activation and breast cancer metastasis and may serve as a prognostic marker of poor outcomes in HER2+ patients." (PMID 39769140, 2024). "Furthermore, curcumin treatment has been shown to block cell migration in MDA-MB-231 breast cancer cells with Her2/Skp2 overexpression." (PMID 37089937, 2023). "Hence, there exists an AKT-Moesin-SKP2 oncogenic axis in breast cancer, which is counteracted by FBXW2." (PMID 37736741, 2023). "Furthermore, SKP2, an oncogene, promotes breast cancer tumorigenesis and radiation resistance through PDCD4 ubiquitination." (PMID 36826085, 2023). "Interestingly, it was shown that AKT kinase, a highly activated oncogenic kinase in breast cancer, phosphorylates both Moesin and SKP2 to activate their oncogenic potential." (PMID 37736741, 2023). "A clinical retrospective study showed that preoperative enhanced expression of SKP2 could predict 94% of breast cancer patients to develop resistance to cyclophosphamide/doxorubicin/5-fluorouracil." (PMID 35831273, 2022). "SKP2 overexpression has been found in a wide range of human malignancies, including lymphomas, prostate cancer, colorectal cancer, melanoma, nasopharyngeal carcinoma, pancreatic cancer, and breast carcinomas." (PMID 35865469, 2022).